TBX4 (T-box transcription factor 4)
Diseases named in the same sentence as TBX4 in open-access papers (continued):
Sharing a sentence is not in itself a finding about the gene and the disease.
pancreatic ductal adenocarcinoma (6 papers, 2011 to 2026). An infiltrating adenocarcinoma that arises from the epithelial cells of the pancreas. "Low expression of TBX4 gene was reported to be associated with worse prognosis among patients with stage II pancreatic ductal adenocarcinoma." (PMID 28978111, 2017). "In stage II pancreatic ductal adenocarcinoma, low TBX4 expression is generally correlated with poor prognosis." (PMID 41439135, 2026). "In intrahepatic cholangiocarcinoma, which shares morphological and biological features with pancreatic ductal adenocarcinoma, tumors with high TBX4 expression were of lower grade, whereas those with low TBX4 expression tended to be high-grade." (PMID 41439135, 2026). "For instance, in both pancreatic ductal adenocarcinoma and normal pancreatic tissues, the TBX4 promoter region displays high CpG island methylation, suggesting that additional factors regulate TBX4 expression in the pancreas." (PMID 41439135, 2026). "Thereafter, further research of Meijuan Zong found that TBX4 was an independent prognostic factor for OS in stage II pancreatic ductal carcinoma (PDC)." (PMID 38413457, 2024). "On the other hand, low expression of TBX4 in patients with pancreatic ductal adenocarcinoma (PDAC) predicted a poor prognosis." (PMID 38413457, 2024). "TBX4 down-regulation is an independent prognostic marker for survival in patients with stage II pancreatic ductal adenocarcinoma." (PMID 37760434, 2023). "Low expression levels of TBX4 indicate a worse prognosis in patients with stage II pancreatic ductal adenocarcinoma (PDAC)." (PMID 31311130, 2019). "Further research in pancreatic ductal adenocarcinoma has shown that TBX4 expression decreases progressively with declining tumor differentiation, raising the possibility that reduced TBX4 levels may serve as an indicator of increasing tumor aggressiveness." (PMID 41439135, 2026). "This study found that TBX4 was overexpressed in pancreatic ductal adenocarcinoma tissue (DAC)." (PMID 38413457, 2024). "This study was designed to investigate the expression of the T-box transcription factor 4 (TBX4), a tumor biomarker that was previously identified by proteomics, in pancreatic ductal adenocarcinoma (PDAC) and evaluate its clinical utility as a potential prognostic biomarkers for PDAC." (PMID 21954337, 2011).
interstitial lung disease (4 papers, 2020 to 2025). A diverse group of lung diseases that affect the lung parenchyma. "In all patients where a pathogenic variant in TBX4 was detected, the clinical expressivity was highly variable, including an initial suspicion of PVOD, interstitial lung disease, pulmonary vascular abnormalities, and CHD." (PMID 33007923, 2020). "FEV1 and FVC were markedly reduced in one patient with additional interstitial lung disease (non-specific interstitial pneumonia by biopsy) attributed to TBX4-mutation and in two patients with airway compression attributed to enlarged pulmonary arteries." (PMID 37441704, 2023). "Further investigations are needed to address the relation between TBX4 or other PAH genes and interstitial lung diseases." (PMID 32348326, 2020). "The results of a recent randomized controlled phase 2 trial of HCQ in 35 patients with various forms of interstitial lung disease (caused by the pathogenic variants of SFTPC, ABCA3, NKX2.1, TBX4, COPA, etc.)did not identify an overall HCQ treatment effect." (PMID 41181172, 2025).
bladder cancer (3 papers, 2020 to 2026). "Moreover, TBX4 has been identified as a potential biomarker for disease progression in bladder cancer, with its methylation status linked to tumor advancement, though specific details are yet to be clarified." (PMID 41439135, 2026). "A study of a total of 119 bladder cancer samples analyzed by Infinium methylation array showed that TBX4 was differentially methylated in bladder cancer and was related to disease progression." (PMID 32688456, 2020). "Additionally, TBX4 contributes to tumorigenesis in cancers such as pancreatic, lung, and bladder cancers, where recent studies suggest DNA methylation as a primary mechanism underlying TBX4 suppression, positioning it as a promising prognostic marker." (PMID 41439135, 2026).
breast carcinoma (3 papers, 2011 to 2023). "TBX4 is located on chromosome 17q23, which has been shown to be amplified in breast cancer and pancreatic cancer." (PMID 21954337, 2011). "TBX4 and CYP24A1 are overexpressed in breast cancer and are associated with breast cancer risk." (PMID 37426199, 2023).
lung adenocarcinoma (3 papers, 2023 to 2026). A carcinoma that arises from the lung and is characterized by the presence of malignant glandular epithelial cells. "Studies suggest that the TBX4-specific methylation marker cg14823851 demonstrates high sensitivity and specificity for distinguishing lung adenocarcinoma from squamous cell carcinoma." (PMID 41439135, 2026). "TBX4 is a tumor suppressor in lung adenocarcinoma and NSCLC whose expression is regulated by a methylating pattern, avoiding its inhibition of cell growth and proliferation or the induction of apoptosis." (PMID 36661515, 2023). "Similarly, TBX4 has been reduced by fourfold and tenfold in lung adenocarcinoma and squamous cell carcinoma, respectively." (PMID 38413457, 2024).
non-small cell lung carcinoma (3 papers, 2019 to 2026). A group of at least three distinct histological types of lung cancer, including non-small cell squamous cell carcinoma, adenocarcinoma, and large cell carcinoma. "But in most patients with non-small cell lung cancer, low TBX4 expression is largely reported to be associated with poor prognosis." (PMID 41439135, 2026). "Even though in certain subsets of patients with non-small cell lung cancer, high TBX4 expression has been associated with poor prognosis." (PMID 41439135, 2026).
osteoarthritis (3 papers, 2023 to 2025). A noninflammatory degenerative joint disease occurring chiefly in older persons, characterized by degeneration of the articular cartilage, hypertrophy of bone at the margins and changes in the synovial membrane. "Several other genes are implicated in DDH but currently have a sparse association with human osteoarthritis in the literature, including BMS1, HOXD9, TBX4, TENM3, and PAPPA2." (PMID 41019141, 2025). "Among them, RUNX2 and T-Box Transcription Factor 4 (TBX4) are major regulators of chondrogenesis and have previously been identified as effector genes for osteoarthritis." (PMID 40724902, 2025). "Several other genes implicated in DDH and/or FAI but with a sparse association with human osteoarthritis in the literature, including BMS1, HOXD9, TBX4, TENM3, PAPPA2, and HOXB9, should be further investigated to elucidate their role in osteoarthritis development." (PMID 41019141, 2025).
Pulmonary hypoplasia (3 papers, 2020 to 2024). "Recently, TBX4 mutations have been found in neonates with pulmonary hypoplasia and others developmental lung disease (acinar dysplasia, congenital alveolar dysplasia), supporting TBX4’s involvement in the embryonic development of the lung." (PMID 38443964, 2024). "TBX4 variants have also been reported in children with severe pulmonary hypoplasia." (PMID 36085161, 2022). "Not all patients harbouring deleterious variants in TBX4 fit neatly into Group 1 PH, some individuals with heterozygous mutations in TBX4 or large deletions encompassing TBX4 were characterised by death in infancy secondary to acinar dysplasia, congenital alveolar dysplasia and pulmonary hypoplasia." (PMID 33256119, 2020).
congenital heart disease (2 papers, 2017 to 2020). A heart disease that is present at birth. "Pediatric PAH due to TBX4 mutations is typically associated with musculoskeletal disorders, congenital heart disease and intellectual disability." (PMID 32348326, 2020). "Variations in NOTCH2, NOTCH3, TTN, TBX4, TBX10, TBX18, and TBXAS1 are associated with congenital heart disease." (PMID 29381953, 2017).
dysplasia (2 papers, 2025). A usually neoplastic transformation of the cell, associated with altered architectural tissue patterns. "A de novo missense mutation in the TBX4 gene (p.E86Q) was identified in a deceased newborn with severe acinar dysplasia of the lungs, suggesting a novel association between TBX4 mutations and this condition." (PMID 40066229, 2025). "Although rare, TBX4-mediated pulmonary hypoplasia with acinar or alveolar dysplasia is an important diagnosis to consider in newborns with unexplained respiratory distress." (PMID 40008593, 2025).
Holt-Oram syndrome (2 papers, 2010 to 2014). Holt-Oram syndrome (HOS) is the most common form of heart-hand syndrome and is characterized by skeletal abnormalities of the upper limbs and mild-to-severe congenital cardiac defects. "Mutations in human, TBX5 and TBX4, areassociated with Holt-Oram syndrome (HOS), and SmallPatella syndrome (SPS),respectively, and both syndromes are characterised by various limb defects in additionto other abnormalities." (PMID 20152185, 2010). "Mutations in human TBX5 cause Holt-Oram Syndrome (HOS OMIM142900), a disorder characterised by upper limb and heart abnormalities and mutations in TBX4 cause Small Patella Syndrome (SPS OMIM 147891), a disorder characterised by knee, pelvis and toe defects." (PMID 24651482, 2014).
Intellectual disability (2 papers, 2020). "As these CNVs often include additional genes located in proximity to the TBX4 gene, they often cause additional features, such as intellectual disability and congenital defects." (PMID 33066286, 2020).
systemic lupus erythematosus (2 papers, 2021 to 2026). An autoimmune multi-organ disease typically associated with vasculopathy and autoantibody production. "Moreover, TBX4 play a key role in systemic lupus erythematosus (SLE) disease pathogenesis through mediating abnormal T cell activity." (PMID 34869721, 2021).
Amelia (1 paper, 2025). Congenital absence (aplasia) of one or more limbs. "To date, TBX5 has been associated with upper amelia, TBX4 with lower amelia, and WNT3, WNT7A and RSPO2 with tetra-amelia syndromes in humans (and cattle, for RSPO2)." (PMID 40131457, 2025).
Apert syndrome (1 paper, 2026). Apert syndrome (AS) is a frequent form of acrocephalosyndactyly, a group of inherited congenital malformation disorders, characterized by craniosynostosis, midface hypoplasia, and finger and toe anomalies and/or syndactyly. "Dysregulation of TBX4 is linked to severe human conditions, such as Apert syndrome, PAH, and lung developmental disorders." (PMID 41439135, 2026). "In humans, the TBX4 gene has been implicated in the pathogenesis of Apert syndrome, a rare form of acrocephalosyndactyly characterized by craniofacial abnormalities, limb deformities, and intellectual disability." (PMID 41439135, 2026).
breast tumors (1 paper, 2020). "Located within the inactive TADs, five of the six aforementioned non-ATC loci (except EFCAB3) were highly methylated at shore regions of CpG island promoters (i.e., TBX2, TBX4, MRC2, and MARCH10) and non-CpG island promoter (i.e., NACA2) in 77 breast tumors compared to 10 normal controls (ref. #)." (PMID 32408897, 2020).
cleft palate (1 paper, 2020). Cleft palate is a fissure type embryopathy that affects the soft and hard palate to varying degrees. "Gene- environment interactions such as potential interaction between TBX4 (chromosome17q21-q22) and dietary folate might also contribute to the occurrence of cleft palate." (PMID 32850599, 2020).
colon cancer (1 paper, 2011). "Additionally, different from TBX5 expression in colon cancer, the expression of TBX4 in PDAC seems not to be DNA methylation-regulated." (PMID 21954337, 2011).
knee osteoarthritis (1 paper, 2025). "More recently, TBX4 has been identified as a central transcriptional regulator of cartilage degeneration in knee osteoarthritis, having important roles in chondrogenesis and embryonic limb morphogenesis." (PMID 40724902, 2025).
lung squamous cell carcinoma (1 paper, 2024). "Then we used Human Protein Atlas to determine the expression of TBX2, TBX3, TBX4 and TBX5 in lung squamous cell carcinoma tissues." (PMID 38413457, 2024).
pancreatic cancer (1 paper, 2011). "Moreover, the promoter methylation status in PDAC tumors and normal adjacent pancreas tissues was also examined to determine whether TBX4 expression in pancreatic cancer was epigenetically controlled." (PMID 21954337, 2011). "However, the clinicopathological and prognostic significance of TBX4 for PDAC patients have not been well characterized; most resectable pancreatic cancer are in stage II, and there is very little information on the prognosis of this subgroup of PDAC patients." (PMID 21954337, 2011).
pulmonary veno-occlusive disease (1 paper, 2022). "Patients with heritable pulmonary veno-occlusive disease (PVOD) carry pathogenic variants in the gene EIF2AK4, while in patients with congenital heart disease associated PAH and some paediatric cases of PAH mutations were identified in the transcription factors SOX17 and TBX4." (PMID 35346192, 2022).
right ventricular dilation (1 paper, 2026). "Depletion of a single Tbx5 allele in addition to both Tbx4 alleles exacerbated histologic phenotypes, with worsened right ventricular dilation." (PMID 42044173, 2026).
sirenomelia (1 paper, 2012). Sirenomelia is a rare, genetic, developmental defect during embryogenesis disorder characterized by fusion of the lower limbs and associated with some degree of lower extremity reduction and persistent vitelline artery. "The decrease of Tbx4 expression in the hindlimb bud by defective BMP4 signaling could be a one of the causative factors for the defective skeletal elements in sirenomelia." (PMID 23028455, 2012).
Wilms tumor (1 paper, 2026). An embryonal neoplasm characterized by the presence of epithelial, mesenchymal, and blastema components. "Interestingly, in a Wilms tumor patient harboring a WT1 mutation, pulmonary metastases displayed elevated TBX4 expression following six months of chemoradiotherapy, implying a potential role for TBX4 in regulating tumor metastasis and therapeutic response." (PMID 41439135, 2026).
tumor (12 papers, 2007 to 2026). "Accumulating evidence indicates that TBX4 expression is significantly associated with tumor grade, prognosis, and overall survival across a variety of cancers." (PMID 41439135, 2026). "This cluster was enriched in genes involved in differentiation and developmental processes (for example, SOX1 and SOX9, HOXD3 and HOXD8, and TBX4) and genes implicated as tumor suppressors (for example, SOX1 and SOX17, TSHZ3, WT1-AS, and FGF14)." (PMID 40931149, 2025). "It is emerging as a potential tumor suppressor, with studies reporting significant correlations between reduced TBX4 expression and advanced tumor grade, poor prognosis, and decreased overall survival in several cancer types." (PMID 41439135, 2026). "The data suggested that TBX4 was downregulated in tumor tissue samples (mean dCT of tumors vs. normal tissues: 0.01 vs. 0.06, p < 0.0001)." (PMID 31311130, 2019). "This list included NKX2-1 and TBX4, both of which have tumor suppressor functions." (PMID 33083012, 2020). "Comparison of primary tumor and metastasis cells from the same patient revealed up‐regulation of RELN and TBX2,TBX4 and TBX5 genes and down‐regulation of several HOXD genes." (PMID 29542868, 2018). "We identify NKX2-1 and TBX4 inactivation as early tumor suppressor events in normal non-ciliated lung epithelial cells from smokers." (PMID 33083012, 2020). "The expression levels of PPM1E were very low across all 26 tumour samples and, additionally, both PPM1E and TBX4 showed highest expression levels in non-amplified tumour samples." (PMID 17353917, 2007). "We found that the expression level of TBX4 was related to TNM stage but not age or tumor size." (PMID 31311130, 2019). "For instance, according to single-cell DE analysis, TFs such as TBX4 and FOXJ1, both with important roles in lung tissue development, were not underexpressed in tumor cells, yet they were found to be inactivated according to SCIRA." (PMID 33083012, 2020).
cancer (11 papers, 2018 to 2026). A tumor composed of atypical neoplastic, often pleomorphic cells that invade other tissues. "Also, a recent study demonstrated down-regulation of TBX4 in carcinoma-associated fibroblasts of NSCLC." (PMID 30866410, 2019). "Collectively, these findings highlight the complex role of TBX4 in cancer initiation, progression, and metastasis, with its expression levels and methylation status emerging as potential biomarkers for cancer diagnosis and therapy." (PMID 41439135, 2026). "From an epigenetic perspective, TBX4 expression is tightly regulated by DNA methylation, and its methylation status has emerged as a prognostic indicator in multiple cancer types." (PMID 41439135, 2026). "A proteomics study revealed the relationship between TBX4 and malignancy progression in cancer for the first time." (PMID 38413457, 2024). "Notably, TBX4 may also function through other mechanisms in cancer." (PMID 41439135, 2026). "MethSig cancer genes were also enriched in developmental genes (for example, PAX6, PAX8 and TBX4), suggesting a potential role for DNA methylation in cell plasticity." (PMID 40931149, 2025). "While for genes GREB1, TBX4 and CYP24A1, both HMs showed higher signals in cancer cell lines than that in normal cells." (PMID 37426199, 2023). "Although the inhibition of the T-box transcription factor Brachyury is shown to downregulate MMP2 and MMP24 in cancer, to date, there are no reports on the direct participation of TBX4 in MMP gene expression." (PMID 31311130, 2019). "While no studies have previously been published in other cancer cell lines for transient overexpression of TBX4 and 5, numerous studies have shown that transient overexpression of TBX2 or TBX3 does specifically affect senescence by targeting the tumor suppressor gene CDKN1A and B, and CDKN2A." (PMID 30425966, 2018).
cardiac diseases (1 paper, 2020). "It is necessary to further investigate the possible involvement of TBX4 in complex cardiac diseases such as CHD and ILD, and how it can contribute to increasing the risk of development of PH in these individuals." (PMID 33007923, 2020).
connective tissue diseases (1 paper, 2021). "Thus, the relationship between TBX4 variants and connective tissue diseases remains unclear." (PMID 34199176, 2021).
TBX4 also shares sentences with these, for which no sentence is quoted: pulmonary hypertension (7 papers); asthma (2); developmental delay (2); microcephaly (2); primary pulmonary hypoplasia (2); respiratory failure (2); alveolar capillary dysplasia (1); anorectal malformation (1); atrial septal defect (1); Cirrhosis (1); dislocation (1); emphysema (1); Hip dysplasia (1); intrahepatic cholangiocarcinoma (1); musculoskeletal disorders (1); Patent ductus arteriosus (1); skeletal dysplasia (1); spondyloepiphyseal dysplasia (1); squamous cell carcinoma (1); ventricular septal defect (1).